INS (insulin)
Diseases named in the same sentence as INS in open-access papers (continued):
Sharing a sentence is not in itself a finding about the gene and the disease.
diabetes (continued). "An experimental study that characterized the enamel hypoplasia in the offspring of rats with alloxan-induced diabetes mellitus led to research using pregnant rats supplemented or not with insulin and controls in which sterile saline was given instead of alloxan or insulin." (PMID 30811464, 2019). "However, the patient had persistent hyperglycemia which required insulin therapy, a history of HH and relatives with autoantibody-negative diabetes." (PMID 29739729, 2019). "Type 2 diabetes mellitus (T2DM) is a chronic metabolic disease whereby various physiologic and metabolic pathways that occur simultaneously to ensure glycemic homeostasis are affected, truncated and worsen over time due to insulin resistance and beta-cell function decline." (PMID 31775302, 2019). "Regardless of the type of diabetes, altered insulin signaling in diabetic individuals leads to profound, but similar, alterations in metabolism, which is characterized by reduced insulin-dependent glucose uptake and utilization, and exacerbated usage of lipids as metabolic substrates." (PMID 31212580, 2019). "However, it is a well-known fact that claims data leads to an overestimation of the prevalence, also because other forms of diabetes, when no insulin therapy is prescribed, are erroneously categorised as type 2 diabetes." (PMID 35146246, 2019). "In unadjusted analyses, there was a stepwise increase in the rates of each of the primary composite outcome, HF hospitalization, CV death, and all‐cause death across the no diabetes (reference group), non‐insulin‐treated diabetes, and insulin‐treated diabetes groups." (PMID 31271255, 2019). "As compared to the patients in cluster 2, those in cluster 1 had no diabetes symptoms (0 of 888 vs. 498 of 516, p < 0.01), had a lower HbA1c (7.6% vs. 11.6%, 60 mmol/mol vs. 103 mmol/mol, p < 0.01), and required less often insulin therapy (62 of 816 vs. 315 of 518, p < 0.01)." (PMID 31291970, 2019). "Over the past three decades, newer technologies have been designed to help patients with diabetes manage their treatment regimens, including continuous glucose monitoring (CGM) systems, insulin pumps, sensor-augmented pump therapy with insulin suspend features, and insulin bolus calculators." (PMID 31888691, 2019). "Despite reduced insulin costs, many patients with diabetes could not afford the additive expenses of monitoring, medicines, and travel." (PMID 31116677, 2019). "Consequently, these patients are typically lean individuals and suffer from ketoacidosis, since lipolysis is not inhibited by insulin and the free fatty acids are released from adipocytes and converted into ketones in the liver." (PMID 31658729, 2019). "While Type 1 diabetes mellitus (T1DM) results from genetic, environmental, or immune dysfunction factors leading to pancreatic β-cell destruction depriving the organism from endogenous insulin, Type 2 diabetes mellitus (T2DM) is characterized by peripheral insulin resistance." (PMID 31466386, 2019). "Despite more consistently reduced insulin costs in the BoP areas, many patients with diabetes could not afford the combined direct expenses of regular monitoring, testing, medical consultations and medicine." (PMID 31116677, 2019). "In addition to improving hippocampal function in animals with central STZ-induced neurotoxicity, exenatide treatment improves hippocampal-dependent spatial memory in rats made insulin resistant with a high fructose diet and in a mouse model of peripheral STZ-induced diabetes." (PMID 31057368, 2019). "Insulin requirements and pill burden were markedly reduced in Case 3 after sleeve gastrectomy, although lack of remission was predictable given the longevity of type 2 diabetes mellitus and preoperative insulin dosage." (PMID 31072397, 2019).
diabetes (continued). "In fact, it must be pointed out that despite the newer antidiabetic therapeutic strategies, almost 30% of patients with T2D are currently treated with insulin because the duration of diabetes is still a strong, independent determinant of insulin use, still lacking disease-modifying drugs." (PMID 31513665, 2019). "Leptin also has a glucose-lowering effect by a mechanism independent of insulin in uncontrolled diabetes, and it normalizes the hepatic glucose production by increasing glucose uptake rate in peripheral tissues such as heart, brown adipose tissue and skeletal muscles." (PMID 31231496, 2019). "Also opposite of obesity, the enhanced transport of insulin across the BBB in the streptozotocin-model of diabetes was not due to changes in serum factors." (PMID 31213970, 2019). "In an individual without diabetes, glucose provision for exercise originates predominately from the liver as a result of increased levels of glucagon and reduced circulating levels of insulin." (PMID 31258513, 2019). "A similar study with STZ-induced (90 mg/kg, i.p.)diabetes in Long Evan rats showed better performance of MO ethanolic leaf extract as compared with glibenclamide, although MO-treated diabetic animals showed no changes in insulin levels." (PMID 31810205, 2019). "For STUDY 2, we recruited 10 subjects without diabetes who underwent an insulin tolerance test." (PMID 31496922, 2019). "In addition to worse patient‐reported outcomes, individuals with diabetes, especially those treated with insulin, had worse clinical outcomes compared to patients without diabetes." (PMID 31271255, 2019). "We found a greater variation in overall scores for different confidence levels, however, this could be due to the questionnaire addressing specific insulin topics, rather than diabetes in general." (PMID 30704103, 2019). "In our study, patients with and without thyroid nodules had similar incidences of diabetes, hypertension, angiotensin-converting enzyme inhibitors, angiotensin receptor blockers, beta blockers, oral antidiabetic drugs, and insulin use, as well as smoking history." (PMID 31203592, 2019). "Furthermore, our study provides additional evidence that pathogenic variants in INS and HNF genes play critical roles in childhood-onset patients with antibody-negative but insulin-requiring diabetes." (PMID 31365591, 2019). "We know that the chosen patient platform, the Diabetes Diary, is not the optimum app for all diabetes patients, as it lacks important features such as the insulin type, blood pressure, polypharmacy, and integration into glucometers and physical activity trackers for automatic data transmission." (PMID 31290396, 2019). "This highlights the great advantage of non-injection insulin therapy routes for diabetes treatment." (PMID 31257946, 2019). "The serum insulin level and HOMA-IR were determined in the C1 group and the DM group to confirm the development of diabetes." (PMID 31308875, 2019). "Additionally, a sub‐analysis of type‐2 DM patients revealed that insulin‐induced eNOS activation was significantly lower in diabetics who had CAD than those who did not." (PMID 30885039, 2019). "Furthermore, compared to those without diabetes, both non-insulin dependent (mHR=1.78; 95% CI, 1.32-2.42) and insulin –dependent (mHR=2.58; 95% CI, 1.61-4.15) diabetics were more likely to have an ischemic stroke." (PMID 31127075, 2019). "The recent National Diabetes Registry, which tracks the care and management of DM in MOH health clinics, reported an increase of over 80% in insulin use within 4 years, from 2009 until 2012." (PMID 31514391, 2019). "Moreover, it is worth mentioning that the patient was not receiving any enteral nutrition since admission and her diabetes was only being treated with correctional sliding scale insulin while in the intensive care unit." (PMID 31259114, 2019).
diabetes (continued). "The number of adults with Type 2 diabetes prescribed insulin in Kenya is also not known, although a household survey performed in Kibera, an informal settlement in Nairobi, estimated that, for those with a formal diagnosis of diabetes, 22.6% used insulin." (PMID 31116677, 2019). "Considering the different tools for diabetes management, SMBG is one of the most important ways to obtain adequate glycemic control in patients with T1D, primarily because it helps to guide patients and providers in adjusting their insulin dose on a daily basis." (PMID 31236141, 2019). "The present meta‐analysis reported that young patients with suboptimally‐controlled type 1 diabetes mellitus and treated with CSII regimen undertook Ramadan fasting with lower rates of hyperglycemia, ketosis and breaking fast compared with those treated with either premixed insulin or MDI regimen." (PMID 30938074, 2019). "Another mechanism by which a lack of L‐serine could affect diabetes development is by affecting mitochondrial function, which is known to influence both insulin secretion and sensitivity." (PMID 31344283, 2019). "To examine the effects of diabetes on β-cell metabolism, we used the βV59M mouse model in which tamoxifen-inducible expression of a constitutively open ATP-sensitive potassium (KATP) channel specifically in pancreatic β-cells renders the β-cell electrically silent and inhibits insulin secretion." (PMID 31171772, 2019). "Indeed, RAS is intrinsic to pancreatic islets and insulin-targeted tissues including adipose, skeletal muscle and liver, whereas both clinical and basic studies demonstrated that RAS blockade improves glucose homeostasis and prevents diabetes." (PMID 31001119, 2019). "Currently it is not clear how human insulin protects NOD mice from diabetes." (PMID 31821343, 2019). "As a tool to aid in the management of type 1 diabetes, patients with type 1 diabetes can use the insulin pump along with RT-CGM to monitor their blood glucose levels, to reduce hypoglycemia, and to reduce insulin dosage or to monitor preterm infants delivered by women affected by diabetes." (PMID 30789351, 2019). "However, the currently available drugs, diet control, insulin injections, and other treatments do not prevent the occurrence of diabetes or the development of various chronic complications." (PMID 32010641, 2019). "Although some viewed insulin as a cure for diabetes, this was surely not the case." (PMID 30357355, 2019). "Type 2 diabetes (T2D), the most common form of diabetes accounting for 90% to 95% of cases, develops when the pancreatic beta cells do not produce enough insulin to overcome insulin resistance in peripheral tissues involved in glucose absorption, metabolism, and removal." (PMID 30357856, 2019). "Another study, using male Wistar rats with alloxan-induced diabetes (120 mg/kg, i.p.)and treated with MO methanolic leaf extract, showed a significant reduction in glycaemia and a significant increase in insulin levels as compared with non-treated diabetic animals." (PMID 31810205, 2019). "Although diabetes primarily could be seen as a disease in which the insulin secretion is not sufficient compared with insulin sensitivity in critical organs, the exact mechanisms leading to type 2 diabetes are not known." (PMID 31446444, 2019). "Unfortunately, despite increasing number of studies, which relate products of lipid peroxidation to the etiology of diabetes mellitus, the specific role of the isoprostane pathway of autoxidation of polyunsaturated fatty acids (PUFAs) in the regulation of insulin secretion has not been identified." (PMID 30450940, 2019). "In addition, Wang’s investigation showed that Tilapia skin gelatin hydrolysate (TSGH) has high in vitro DPP-IV inhibitory activity; after 30 days’ daily administration of TSGH, glucose tolerance in rats with STZ-induced diabetes improved, and GLP-1 and insulin secretion were enhanced." (PMID 30678216, 2019).
diabetes (continued). "Additionally, impaired glucose‐stimulated insulin release was accompanied by elevated triglycerides and LDL levels in geriatric monkeys as previously observed, suggesting that geriatric African green monkeys represent a useful test system in diabetes research." (PMID 30357856, 2019). "When exhausted β-pancreatic cells can no longer overproduce insulin, diabetes evolves." (PMID 31126031, 2019). "Moreover, the reported findings further support our data that insulin treatment does not completely restore Pomc expression in the ARC during diabetes." (PMID 30503832, 2019). "Additionally, Diabetes UK, Trend UK and RCN’s 2014 position statement presented evidence that suggests that DSNs, especially those with Nurse Prescribing skills, significantly reduce insulin error, with a consequential reduced LOS." (PMID 31391081, 2019). "The following variables that were significant in the univariate analysis were included in the prediction model: presence or absence of DFU, income, duration of diabetes, use of insulin only, use of a combination of insulin and oral medications, and smoking status." (PMID 31796044, 2019). "The elevated risks were attenuated, but remained significantly higher, in the other patients with diabetes not receiving insulin, with a fully adjusted HR of 1.46 (95% CI 1.14–1.86; P = 0.003) for sudden death and 1.83 (95% CI 1.36–2.46; P < 0.001) for pump failure death, respectively." (PMID 31271255, 2019). "The evidence is incomplete, but it currently suggests that people without diabetes but with normal fasting glucose and insulin sensitivity can achieve marginally greater success on low-fat regimens, preferably higher in protein, provided very high GLs are avoided." (PMID 30861997, 2019). "We found that 60% of the adult cohort and 100% of the elderly cohort presented with comorbidities, with diabetes mellitus in 10% (1/10) and 54% (7/13) of cases (mainly early-stage, 6 non-insulin, and 2 insulin-dependent), respectively, followed by hypertension and other cardiovascular complications." (PMID 31781089, 2019). "However, as this study was on female mice without diabetes, further study is required to comprehensively establish the link between insulin signaling in male with diabetes and central neuroendocrine reproductive function." (PMID 31620084, 2019). "Additionally, generic assessment tools do not account for intentional insulin under dosing or omission to control weight, a diabetes-specific compensatory behavior reported in up to 37% of females with T1D and associated with a three-fold mortality rate." (PMID 30675355, 2019). "In conditions of diabetes, exosomes play important roles in the pathological processes in both T1DM and T2DM, such as connecting the immune cell response to pancreatic tissue injury, as well as adipocyte stimulation to insulin resistance of skeletal muscle or liver." (PMID 31398847, 2019). "This clearly supraphysiological glucose concentration was chosen as it was reported for mouse islets that 25 mmol/L glucose with or without palmitate inhibited the 1st phase of insulin release after short-term incubation (3 d) similar to the situation described for type 2 diabetes mellitus." (PMID 31827698, 2019). "The higher insulin concentrations might contribute to hypoglycemia in GD patients with or without diabetes." (PMID 30515677, 2019). "As SCD1 inhibition may induce insulin sensitivity in muscle and BAT, it is therefore plausible to explore the use of SCD as a potential therapeutic target for the treatment of insulin resistance and diabetes." (PMID 31554181, 2019). "Our study also limited the lack of data on diabetes treatments except insulin." (PMID 30890169, 2019). "Administration of A. reticulata seed extract to diabetes rats significantly restored the alterations in the levels of body weight, food and water intake, fasting blood glucose (FBG), insulin levels, insulin sensitivity, HbA1c, HOMA-IR, islet area and insulin positive cells." (PMID 31708869, 2019).
diabetes (continued). "While BA have a hyperinsulinaemic response to glucose, reduced hepatic insulin extraction rather than differences in beta cell function may be the primary determinant of ethnic differences in diabetes pathophysiology in adulthood." (PMID 31781667, 2019). "The following variables that were significant in the univariate analysis were included in the prediction model: age, presence or absence of DFU, duration of diabetes, use of insulin only, use of a combination of insulin and oral medications, and smoking status." (PMID 31796044, 2019). "Glucose, insulin or lipid levels remained low, without the development of diabetes." (PMID 29652901, 2018). "A recent study investigating the fecal microbiota of cats with diabetes and treated with insulin, showed no significant changes in fecal microbial composition although the abundances of Bacterioides and Bifidobacterium trended (P < 0.10) toward decreasing with the disease." (PMID 29971046, 2018). "Adults who reported having type 1 diabetes but reported not using insulin were classified as having type 2 diabetes, as were persons who reported type 2 diabetes, unknown diabetes type, or who would not report diabetes type." (PMID 29596402, 2018). "Findings from a few small intervention studies targeting depressed individuals without diabetes at baseline have shown that depression treatment improves a marker of prediabetes known as insulin sensitivity, particularly among patients whose achieved depression remission." (PMID 30138433, 2018). "Suppressing Gckr by small molecule inhibitors of GKRP could reduce blood glucose levels in rodent models of diabetes without short-term side effects on insulin or lipids." (PMID 30687391, 2018). "If we assume that this insulin-regulated ENPP1 expression exists in cells responsible for bone health, we probably can come up with a hypothesis to explain part of the bone health problems in patients with diabetes." (PMID 29513794, 2018). "Accuracy was unaffected by the type of diabetes (T1D, T2D, GDM), whether or not insulin was used, the stage of pregnancy, the age or BMI of the participants, thus making the system suitable for women with diabetes during pregnancy." (PMID 29470094, 2018). "Despite the fact that Asian Indians are highly insulin resistant and more prone to develop T2DM and associated vascular complications, there is virtually lack of data on the role of lncRNAs in the clinical diabetes setting." (PMID 30139387, 2018). "27/79(34%) insulin-treated patients had >1 documented hypoglycaemia episode, compared to 4/85(5%) sulphonylurea-treated patients, 2/121(2%) metformin-only treated patients, and none without diabetes, p < 0.001." (PMID 28918198, 2018). "Moreover, animals with diabetes are more prone to pose negative effects on brain insulin signaling under CUMS condition." (PMID 30622594, 2018). "Besides its beneficial role against diabetes, PPAR-γ also increases adiponectin, which orchestrates both glucose and lipid homeostasis; resulting in the reduction of lipid accumulation and improvement of insulin sensitivity." (PMID 30072896, 2018). "During sleep deprivation, alterations in glucose tolerance and insulin sensitivity occur from morning to evening in people with type 2 diabetes mellitus as well as obese people without type 2 diabetes due to a disturbance of the circadian changes in cortisol causing reduced beta cell sensitivity." (PMID 29637032, 2018). "Dual or triple therapy with insulin (usually a basal insulin) in combination with metformin or other noninsulin antihyperglycemic medication is recommended for people with type 2 diabetes mellitus (T2DM) who do not attain glycemic target on noninsulin antihyperglycemic medications alone." (PMID 29760944, 2018). "Therefore, it is postulated that in diabetes, there may be a secondary defect of epimerase, which impairs the physiological conversion of MI to DCI, stimulated by insulin." (PMID 30513929, 2018).